RFC4 (replication factor C subunit 4)
Description:
Subunit of the replication factor C (RFC) complex which acts during elongation of primed DNA templates by DNA polymerases delta and epsilon, and is necessary for ATP-dependent loading of proliferating cell nuclear antigen (PCNA) onto primed DNA. The RFC4 subunit probably functions as a scaffold on which the other complex components can assemble.
Synonyms: RFC37; A1; MRMNS
Tractability: Small molecule: a structure with a bound ligand is known. PROTAC: ubiquitination databases record sites on it; its protein half-life has been measured.
Gene: Protein-coding gene on chromosome 3 (186,789,880 to 186,807,058, reverse strand). Ensembl gene ENSG00000163918.
Subcellular location: Nucleus
Subcellular location (Human Protein Atlas): Nucleoplasm
Pathways (Reactome):
DNA Repair: Dual Incision in GG-NER; Dual incision in TC-NER; Gap-filling DNA repair synthesis and ligation in GG-NER; Gap-filling DNA repair synthesis and ligation in TC-NER; HDR through Homologous Recombination (HRR); HDR through Single Strand Annealing (SSA); PCNA-Dependent Long Patch Base Excision Repair; Presynaptic phase of homologous DNA pairing and strand exchange; Processing of DNA double-strand break ends; Recognition of DNA damage by PCNA-containing replication complex; Termination of translesion DNA synthesis; Translesion Synthesis by POLH; Translesion synthesis by POLI; Translesion synthesis by POLK; Translesion synthesis by REV1
Cell Cycle: Activation of ATR in response to replication stress; G2/M DNA damage checkpoint; Polymerase switching on the C-strand of the telomere
DNA Replication: Polymerase switching
Disease: Impaired BRCA2 binding to RAD51
Gene Ontology:
Molecular function: DNA clamp loader activity; protein binding; single-stranded DNA helicase activity; ATP binding; ATP hydrolysis activity; DNA binding; enzyme binding
Biological process: DNA-templated DNA replication; positive regulation of DNA-directed DNA polymerase activity; DNA repair; DNA replication; DNA replication checkpoint signaling; DNA strand elongation involved in DNA replication
Cellular component: Ctf18 RFC-like complex; DNA replication factor C complex; Elg1 RFC-like complex; nucleoplasm; Rad17 RFC-like complex; nucleus; chromosome
Genetic constraint (gnomAD): Loss-of-function variants: 33 observed, 40.24 expected, observed/expected ratio (o/e) 0.82, 90% interval 0.62 to 1.1. The upper end of that interval is the gene's LOEUF score, 1.1, which puts it in group 4 of 6, group 1 being the genes least tolerant of losing a copy. Missense variants: 428 observed, 396.9 expected, observed/expected ratio (o/e) 1.08, 90% interval 1 to 1.17. Synonymous variants: 144 observed, 138.23 expected, observed/expected ratio (o/e) 1.04, 90% interval 0.91 to 1.2.
Homologues: Orthologues: chimpanzee RFC4 (99% identical), macaque RFC4 (98% identical), pig RFC4 (96% identical), dog RFC4 (96% identical), rabbit RFC4 (94% identical), guinea pig RFC4 (92% identical), rat Rfc4 (91% identical), mouse Rfc4 (91% identical), tropical clawed frog rfc4 (83% identical), zebrafish rfc4 (69% identical), Drosophila melanogaster CG8142 (52% identical), Caenorhabditis elegans rfc-4 (37% identical). Paralogues in human: RFC5 (35% identical), RFC2 (33% identical), RFC3 (25% identical).
Diseases named in the same sentence as RFC4 in open-access papers:
RFC4 is named in the same sentence as 53 diseases in open-access papers, as found by Europe PMC text mining. Sharing a sentence is not in itself a finding about the gene and the disease. The quoted sentences say what the papers report.
cervical carcinoma (15 papers, 2016 to 2025). A carcinoma arising from either the exocervical squamous epithelium or the endocervical glandular epithelium. "The imbalance of CDKN2A, IL1R2, and RFC4 could promote the proliferation of cancer cells, which is closely related to the progress of cervical cancer, and might be a potential diagnostic marker and therapeutic drug targets." (PMID 33833775, 2021). "The expression of RFC4 may also be associated with tumor progression and poor patient survival and is considered to be one of the main driving factors of the cervical cancer cell cycle network." (PMID 34174849, 2021). "The RFC4 has also been identified in previous studies as a tumor suppressor gene and has been associated with poor prognosis in CRC, HCC, cervical cancer, oral tongue squamous cell carcinoma, NSCLC, and esophageal squamous cell carcinoma." (PMID 38504096, 2024). "In silico studies have shown the relationship between Trichostatin A and Vorinostat and RFC4 mRNA expression in cervical cancer." (PMID 38399367, 2024). "Several studies based on TCGA-CESC data have reported the relationship between TOP2A and RFC4 mRNA expression and the prognosis of cervical cancer." (PMID 36352434, 2022). "RFC4 has been reported to be overexpressed in a variety of malignancies, including prostate cancer, cervical cancer, colorectal cancer, and head and neck squamous cell carcinoma." (PMID 34408776, 2021). "The RFC4 gene, which encodes the fourth biggest subunit of RFC complex, has been found to be dysregulated in a variety of cancers, including head-and-neck squamous cell, hepatocellular, colonic, prostate, and cervical carcinomas." (PMID 38645487, 2024). "In addition, RFC4 accelerated G1 to S phase progression, and promoted the proliferation of cervical cancer cells and the growth of cervical cancer." (PMID 32127942, 2020). "The upregulation of RFC4 was observed in cervical cancer.A study found that RFC4 may be used as a predictor of cancer relapse and survival rate in patients with cervical carcinoma." (PMID 29312619, 2017). "The abnormal expression of RFC4 might be related to the progression of cervical cancer." (PMID 34174849, 2021). "The expression of RFC4 from 3q26 exhibited a high correlation with copy number gain, and 3q gain as a potential marker in the diagnosis of HSIL is frequently found in cervical cancer and its precancerous lesions." (PMID 36352434, 2022). "Survival analysis was performed on the top 10 genes with protein-protein interactions showed that the overall survival (OS) time of CDC45, RFC4 and TOP2A was significantly correlated with the prognosis of cervical cancer." (PMID 34557356, 2021). "The outcomes of this assessment substantiated our preliminary observations, revealing the upregulation of RRM2 and VEGFA, alongside the downregulation of RFC4, EXO1, PCNA, TOP2A, and TYMS in cervical cancer tissues relative to normal cervical epithelial tissues." (PMID 38926832, 2024). "In addition, RFC4 has been proposed as a new surrogate biomarker for identifying higher-grade squamous intraepithelial lesions (HSIL) and HSIL+ in cervical cancer." (PMID 38399367, 2024). "Previous study has shown that RFC4 is highly expressed in cancer tissues such as hepatocellular carcinoma, non-small cell lung cancer (NSCLC), prostate cancer, breast cancer, and cervical cancer." (PMID 35483337, 2022). "In the present paper we identified six putative biomarkers (AURKA, DTL, HMGB3, KIF2C, NEK2, and RFC4) which should be further tested to separate indolent HPV related cervical infections from progressive CIN III lesions and for early diagnosis of cervical cancer." (PMID 26701206, 2016). "Replication factor C subunit 4 (RFC4) plays a critical role in the initiation and progression of some cancers; however, its relationship with tumor-infiltrating immune cells in cervical cancer (CC) has not been comprehensively analyzed." (PMID 40458559, 2025).
breast carcinoma (11 papers, 2008 to 2025). "DTL, ECT2, MTDH, PRC1 and RFC4 have all been previously implicated in breast cancer; SCUBE2 and STK32B deletions have been found to be related to mental deficits in humans; and ZNF533 has been found to be associated with the Hedgehog signaling pathway in Zebrafish." (PMID 20584321, 2010). "In the cohort of cancer patients treated with BI‐2536, RFC4 expression was found to be high in responders with breast cancer." (PMID 39031628, 2024). "We found that RFC4 was highly expressed in responders in the breast cancer cohort after BI‐2536 treatment, and the AUC value of OS after BI‐2536 treatment reached 0.756." (PMID 39031628, 2024). "RFC4 is involved in DNA replication and chromosomal stability, and its upregulation was found in the poor prognostic group of breast cancer." (PMID 29383109, 2017). "Finally, the increase in expression of the genes CCNE1, FANCI, RFC4, CDC6, and YWHAZ associated with poor prognosis in luminal A breast cancer (OS, HR:2.54, CI 1.69–3.82, log rank p = 3.6 × 10−6; RFS, HR:1.84, CI 1.53–2.22, log rank p = 6.5 × 10−11)." (PMID 33925616, 2021). "Furthermore, RFC4 overexpression contributes to the development of breast cancer." (PMID 33662042, 2021). "Moreover, RFC4 was reported as an independent predictor of overall survival in breast cancer." (PMID 33344075, 2020). "Furthermore, we found that DNA repair (P < 0.01) and cell cycle (P < 0.001), were significantly related to RFC4 in HNSCC and breast cancer." (PMID 39673181, 2025).
colorectal cancer (11 papers, 2020 to 2025). A primary or metastatic malignant neoplasm that affects the colon or rectum. "The expression level of RFC4 has also been associated with the progression of colorectal cancer and can be used for prognosis prediction of colorectal cancer." (PMID 40458559, 2025). "RFC4 is frequently overexpressed in colorectal cancer (CRC), and RFC4 overexpression is associated with tumor progression and shorter patient survival, possibly due to RFC4-mediated cell cycle arrest and the regulation of CRC cell proliferation." (PMID 36499305, 2022). "RFC4 is exhibited highly expressed and has significantly increased activity in various malignant tumors, including prostate, cervical, and colorectal cancers." (PMID 40458559, 2025). "Many studies have shown that RFC4 can promote tumor progression and metastasis in lung, nasopharyngeal, hepatocellular and colorectal cancers." (PMID 40612960, 2025). "For example, in colorectal cancer, RFC4 was correlated with tumor progression and predicted prognosis." (PMID 34520390, 2021). "Overexpression of RFC4 commonly occurs in colorectal cancer and higher levels of RFC4 protein expression correlate with a worse overall survival." (PMID 33557274, 2021). "Previous studies showed that the high expression of RFC4 was the biomarker of tumorigenesis, poor survival, as well as chemotherapy resistance of colorectal cancer patients." (PMID 32149105, 2020). "RFC4 is often upregulated in colorectal cancer, which affects the gastrointestinal tract (GIT)." (PMID 38399367, 2024). "In colorectal cancer tissues, the staining levels of RFC1, RFC2, RFC4, and RFC5 protein expression were modest." (PMID 38504096, 2024). "In a previous study, whole-genome RNAi screening showed that RFC4 mediates radiotherapy tolerance in colorectal cancer by promoting repair of non-homologous end connections." (PMID 40458559, 2025). "Furthermore, RFC4 has been shown to serve as a radioresistance factor, facilitating the process of DNA repair mediated by nonhomologous end joining (NHEJ) in cells affected by colorectal cancer." (PMID 38399367, 2024).
hepatocellular carcinoma (7 papers, 2014 to 2025). A malignant tumor that arises from hepatocytes. "The mRNA expression of RFC4 was significantly increased in hepatocellular carcinoma tissues, and the expression of RFC4 was closely correlated with the tumour stage of hepatocellular carcinoma patients." (PMID 39031628, 2024). "Taken together, we found that RFC4 has good prognostic value and potential to be an immunotherapeutic target in hepatocellular carcinoma, therefore, we specifically analysed RFC4 in LIHC." (PMID 39031628, 2024). "In GSK461364, SB‐225002‐treated patients, non‐responders in breast, head and neck, and hepatocellular carcinoma patients were characterized by high expression of RFC4, and the area under the curve (AUC) values of OS exceeded 0.5 in all cohorts." (PMID 39031628, 2024). "Interestingly, a previous study revealed that the downregulation of RFC4 can enhance the cytotoxic effects of doxorubicin and camptothecin in hepatocellular carcinoma cells." (PMID 25407051, 2014). "A study in hepatocellular carcinoma showed that CDC20 and Rfc4 are involved in cancer cell survival, and another study showed that Rfc4 interacts with RPA1 for DNA replication and DNA damage repair." (PMID 39125953, 2024).
liver cancer (6 papers, 2019 to 2025). An epithelial or non-epithelial malignant neoplasm that arises from the liver. "We then observed the expression of RFC4 in liver cancer cell lines from the HPA database and found that it was highly expressed in Huh7 and Hep3B." (PMID 39031628, 2024). "Silencing of RFC4 in various tumours, such as colon, breast and liver cancers, inhibits cells in S‐phase, preventing them from progressing to subsequent mitosis and proliferation, ultimately resulting in reduced tumour cell proliferation." (PMID 39031628, 2024). "To investigate the biological role of RFC4 in the growth of HCC cells, we validated the differential expression of RFC4 in cancer and adjacent tissues in three datasets of liver cancer from the HCCDB database (p < 0.05)." (PMID 39031628, 2024). "RFC4 is involved in DNA replication as a clamp loader, and it’s dysregulation related to the prognosis of patients with liver cancer." (PMID 33516217, 2021). "The silencing of RFC4 expression was able to reduce HepG2 cell proliferation and promote apoptosis, and was also associated with the increased sensitivity of cells to doxorubicin and camptothecin, suggesting RFC4 may be a novel target for liver cancer treatment." (PMID 31534853, 2019). "Bioinformatics analysis has confirmed that RFC4 is a potential therapeutic target for liver cancer." (PMID 40458559, 2025). "Moreover, liver cancer patients with an increased expression level of KIF14 (p = 0.006), PRIM1 (p = 0.013), and RFC4 (p < 0.001) also had poorer outcomes." (PMID 34681056, 2021). "Moreover, among of them, RFC4, ZWINT, UPF3B, NCBP2, ADA, SF3A3 and GTF2H1 are independent prognostic indicators of liver cancer." (PMID 33516217, 2021). "As expected, FEN1 expression was significantly positively correlated with that of MCM2, RFC4, and BIRC5 in TCGA liver cancer tissues, suggesting that FEN1 may be as involved in the development of HCC as are MCM2, RFC4, and BIRC5." (PMID 31534853, 2019). "The expression of FEN1 in TCGA liver cancer tissues was positively correlated with that of MCM2 (r = 0.853, P = 0.000), BIRC5 (r = 0.809, P = 0.000), and RFC4 (r = 0.852, P = 0.000), suggesting that FEN1 may play as important a role in the progression of liver cancer as do MCM2, BIRC5, and RFC4." (PMID 31534853, 2019).
melanoma (5 papers, 2017 to 2024). A malignant, usually aggressive tumor composed of atypical, neoplastic melanocytes. "Like 2A-DUB/MYSM1, the newly-identified MYSM1 interaction partners, HELLS and RFC4/5, have also been implicated in tumorigenesis, specifically in melanoma growth; HELLS is frequently misregulated in a variety of cancers." (PMID 32466590, 2020). "In summary, 294 DEGs between the primary and metastatic skin cutaneous melanoma samples were screened, and four hub genes, CDK1, FOXM1, KIF11, and RFC4, were identified that may be associated with the metastasis of melanoma." (PMID 35906389, 2022). "We found that except for the moderate staining of RFC4 in both primary and metastasis tissues of the melanoma, the other three hub genes showed moderate expression in primary tumor tissues, but showed strong expression in metastatic melanoma tissues." (PMID 35906389, 2022). "The results showed that three hub genes (CDK1, KIF11 and RFC4) were significantly upregulated in metastatic melanoma tissues compared in primary melanoma tissues." (PMID 35906389, 2022). "A previous PPI network analyses conducted in a whole gene expression dataset of 31 primary melanomas and 52 metastases reported a PPI network in which PCNA, CDK1, MAD2L1, RFC4 and BRCA1 genes showed highest degree centrality values among upregulated genes in metastases." (PMID 28030792, 2017). "Similarly, RFC4 and RCF5 are involved in the G2/M checkpoint in tumors, and RFC5 expression correlates with melanoma progression and may affect responses to chemotherapy." (PMID 32466590, 2020).
lung adenocarcinoma (4 papers, 2020 to 2025). A carcinoma that arises from the lung and is characterized by the presence of malignant glandular epithelial cells. "Since RFC4 is a known drug target, the remaining 12 may be new biomarker candidates of drugs for lung adenocarcinoma." (PMID 36605489, 2023). "However, although the expression levels of BRCA1 and RFC4 were higher in lung adenocarcinoma tissues than in adjacent normal tissues, the differences were not significant." (PMID 32607285, 2020). "The research findings indicate that ATR, RFC4, and MCM2 are pivotal genes in the pathogenesis of type 2 diabetes and lung adenocarcinoma." (PMID 40282196, 2025).
lung carcinoma (4 papers, 2021 to 2024). "Conversely, in patients treated with CD‐327, RFC4 expression was high in non‐responders with breast, liver and lung cancer, but was high in responders with gastric cancer and head and neck cancer." (PMID 39031628, 2024). "Consistently, silencing RFC4 significantly suppressed the ability of highly metastatic murine lung cancer cells to form lung metastases when injected intravenously or to develop subcutaneous tumors when injected with various cell numbers ranging from 5 × 103 to 5 × 105 in C57BL/6N mice." (PMID 33976158, 2021). "Some of the predicted master regulators, including PTTG1, RFC4, TRIP13, BUB1B, TTK, and ZWINT are capable of promoting migration, invasion, and metastasis of lung cancer cells." (PMID 36304306, 2022).
colon cancer (3 papers, 2014 to 2024). "Furthermore, by using the BioGPS Gene Expression Atlas, we found that RFC4 expression was highly expressed in colon cancer." (PMID 25407051, 2014). "Next, we confirmed the expression of RAD51C, RFC4, SIRT1, SIRT5, and SMAD3 genes in different colon cancer cell lines." (PMID 39110260, 2024). "RAD51C, RFC4, and SIRT5 exhibited a low differential expression in Caco-2 cells treated with LEVs but a high differential expression in TCGA colon cancer tissue samples." (PMID 39110260, 2024).
osteosarcoma (3 papers, 2021 to 2022). A usually aggressive malignant bone-forming mesenchymal neoplasm, predominantly affecting adolescents and young adults. "RFC4, CDK3, CDC45 and NCAPG were found to be associated with osteosarcoma for the first time in our analysis, and thus could be novel diagnostic/prognostic biomarkers or treatment targets." (PMID 34156352, 2021). "RFC4, along with other genes and microRNAs, might promote osteosarcoma initiation and development." (PMID 36499305, 2022).
gastric cancer (2 papers, 2018 to 2024). A primary or metastatic malignant neoplasm involving the stomach. "Therefore, rs1679709 might influence defective DNA mismatch repair associated mutational signatures in gastric cancer, via regulating the copy number changes in relevant genes like RFC4." (PMID 29923336, 2018).
lung squamous cell carcinoma (2 papers, 2021 to 2024). "The examination of the cBioPortal database produced findings that suggest lung squamous cell carcinoma exhibits the most significant occurrence of genetic mutations in RFC4 among all types of human malignancies, with an approximate change frequency of 32%." (PMID 38399367, 2024).
mesothelioma (2 papers, 2014 to 2024). A usually malignant and aggressive neoplasm of the mesothelium which is often associated with exposure to asbestos. "There are also several similarities with mesothelioma in this respect where overexpression of two or more of CDK7, GTF2H2, PCNA, RFC4, and the RFC5 were shared by the lung tumors." (PMID 25325012, 2014).